YY1 (YY1 transcription factor)
Diseases named in the same sentence as YY1 in open-access papers (continued):
Sharing a sentence is not in itself a finding about the gene and the disease.
tumor (335 papers, 2008 to 2026). "Previous studies have shown that the transcription factor YY1 is associated with tumor progression and metastasis." (PMID 40611320, 2025). "The relationship between YY1 expression levels and the tumor microenvironment was examined in different risk groups of GC patients." (PMID 40088083, 2025). "In this study, we created a new prognostic risk model that combines YY1 expression with clinical variables like age and tumor stage to predict clinical outcomes in GC." (PMID 40088083, 2025). "In tumor‐associated macrophages, YY1 induces a phenotypic shift from antitumor M1 macrophages to immunosuppressive M2 macrophages by inhibiting miR‐125a." (PMID 41322030, 2025). "Particularly in the regulation of tumor immunity, multiple studies have implicated YY1 in the regulation of PD‐L1 expression, though the mechanisms vary." (PMID 41322030, 2025). "YY1 expression was lost in 14.2% of cases, and this loss was significantly associated with larger tumor size, tumor deposits, and higher tumor stage." (PMID 41327312, 2025). "To examine the clinical significance of our findings, we also performed triple‐immunostaining of CD34, α‐SMA, and YY1 on tumor sections derived from our EGFR mutated NSCLC patient cohort." (PMID 39435643, 2024). "Our results are in concordance with results recently published that showed, using TCGA and GEO datasets, that YY1 was expressed at high levels in most malignancies, and its level of expression was statistically associated with the prognosis of tumor patients." (PMID 39684309, 2024). "While the minor allele (A) of rs10025845 is not predicted to result in any TF binding site, the G allele creates a binding site for the YY1 TF, which has also been shown to play a tumor suppressor role in PDAC." (PMID 38308339, 2024). "The overexpression of YY1 has been further linked to tumor cell resistance in cell-mediated immunotherapies." (PMID 39796650, 2024). "Targeting YY1 in KDM5C-deficient tumor cells effectively suppressed cell proliferation and tumorigenesis." (PMID 39433896, 2024). "Among the discovered TFs, YY1 has been implicated in tumor aggressiveness and medication resistance through the regulation of cell cycle control and metastasis-related genes." (PMID 39656775, 2024). "The univariate Cox regression analysis for DFS revealed primary tumor size (p < 0.0001) and high YY1 expression (p = 0.016) as the significantly associated prognostic factors." (PMID 37444605, 2023). "Although autophagy is hugely significant in tumor development, the underlying mechanisms of how YY1 operates in the regulation of autophagy in GC remain undetermined." (PMID 37724907, 2023). "YY1 function is regulated through the IL-4/STAT6 signaling pathway in tumor-associated immune cells." (PMID 37762277, 2023). "YY1 overexpression (pre-miR-30e-5p+ov-YY1 group) attenuated the inhibition of tumor growth caused by pre-miR-30e-5p." (PMID 34998399, 2022). "In most malignancies, YY1 was expressed at high levels, and the level of YY1 expression was statistically associated with the prognosis of tumor patients." (PMID 35791393, 2022). "We used CPTAC dataset to investigate the underlying molecular process of YY1 protein in six tumor types from the perspective of total protein and phosphorylated protein." (PMID 35791393, 2022). "We observed the effects of YY1 mutations in different tumor samples in the TCGA cohort on gene expression." (PMID 35791393, 2022). "In some of these cancers, increased YY1 level is associated with poor prognosis (e.g., prostate and breast), while in others, it induces mechanisms that inhibit tumor progression (e.g., ovarian and colon)." (PMID 35408813, 2022).
tumor (continued). "Because of this, RKIP’s ability towards the NF-kB/YY1/Snail circuit is thought to be the underlying mechanisms of RKIP-mediated inhibition of tumor chemoresistance and immune-resistance." (PMID 34944867, 2021). "YY1 loss-of-function assays demonstrated that YY1 mediates the growth of tumor spheres and expression of CSC markers, such as CD133, STAT3, and integrin-α6." (PMID 33728560, 2021). "YY1 competitively bound to Rb gene to cause the cell cycle to enter the S phase and promote the proliferation of tumor cells." (PMID 34933678, 2021). "The potentiation of YY1 and GSK3β by O-GlcNAcylation will drive changes in metabolism in tumours and tumour microenvironment cells in association with their regulation of the melatonergic pathway." (PMID 33375613, 2020). "First, we utilized a tamoxifen-inducible EC-specific YY1 deficient mouse model and showed that YY1 deletion in ECs inhibited the tumor growth and tumor angiogenesis." (PMID 33235311, 2020). "YY1, a ubiquitously expressed and multifunctional transcription factor, has been implicated in various aspects of tumor growth." (PMID 33235311, 2020). "It has been reported that YY1 in tumor cells was implicated in tumor angiogenesis through driving HIF1-dependent expression and secretion of VEGF in tumor cells." (PMID 33235311, 2020). "Does the increased YY1 in tumours associate with heightened levels of CYP1B1, mGluR5, P2Y1, O-demethylation and CYP2C19, and thereby with the “backward” conversion of melatonin to NAS and TrkB-driven GSC, survival and proliferation?" (PMID 35582450, 2020). "The resulting reduced activity of miR-9 by YY1 causes the activation of nuclear factor-κB (NF-κB), which consequently induces resistance to apoptosis and promotes tumor growth." (PMID 32226547, 2020). "In vitro and in vivo studies have reported the expression of YY1 has been associated with development of a malignant phenotype in some human cancers, tumor progression, metastasis formation, and correlating with poor prognosis and drug/immune resistance." (PMID 31561604, 2019). "Overall, our study is the first attempts to evaluate the potential of combining imaging differences between SM and MM breast patient subgroups and YY1 gene expression, for a better diagnostic analysis of tumor metastasis (see Discussion)." (PMID 31561604, 2019). "Recent studies showed that YY1 is implicated in carcinogenesis and can play either oncogenic or tumor-suppressive roles in tumor development and progression." (PMID 24970812, 2014). "The nitrosylation of YY1 resulted in the loss of its transcriptional activity, a mechanism by which the tumor cells exhibit the repression of both Fas and DR5 receptors." (PMID 25053986, 2014). "The potential mechanisms underlying YY1 mediated tumor progression in PDAC were explored by digital gene expression (DGE) sequencing, signal transduction pathways blockage experiments and luciferase assays." (PMID 24884523, 2014). "The increase in mRNA and protein expression of αSMA was associated with increase of YY1 protein expression in tumor kidney tissues." (PMID 23705901, 2013). "The polycomb transcription factor Yin Yang 1 (YY1) overexpression can be causally implicated in experimental tumor growth and metastasization." (PMID 22047406, 2011). "Additionally, transcriptomic data from public databases indicate that several oncogenes and tumor suppressors related to YY1 in multiple processes associated with tumor growth and development are up- and downregulated in BC vs. normal samples." (PMID 41009346, 2025). "A study showed that YY1 could suppress anti-tumor immunity by enhancing HIF-1α stability in tumor-associated macrophages." (PMID 40867514, 2025).
tumor (continued). "We propose to utilize HPV-positive organoid models and patient-derived xenografts to functionally test whether the competitive displacement of TFAP2 by YY1 drives hallmark cancer phenotypes such as sustained proliferation, invasion, and in vivo tumor growth." (PMID 40953061, 2025). "Notably, high YY1 expression in tumor tissues was often linked to a decrease in immune cell numbers, potentially contributing to immune evasion and poor prognosis." (PMID 40088083, 2025). "The degree of YY1 chromatin recruitment was decreased in KDM5C-deficient tumor cells, and further inhibition of YY1 expression might completely suppress YY1-directed transcription and significantly impair the proliferation of tumor cells." (PMID 39433896, 2024). "Consequently, gaining a comprehensive understanding of the mechanisms underlying YY1’s function as both a tumor promoter and suppressor is of paramount importance." (PMID 38347631, 2024). "Furthermore, it is possible to find cancer subtypes in which YY1 overexpression is associated with cancer progression, and other subtypes in which its overexpression has a tumor-suppressive effect." (PMID 39796650, 2024). "Therefore, YY1 is critical for tumor progression, and increasing evidence suggests a close association between YY1 and cancer." (PMID 39690926, 2024). "Moreover, YY1 upregulation is associated with poor prognosis and aggressive tumor behavior, characterized by increased tumor growth, invasion, and metastasis." (PMID 37444616, 2023). "YY1 has been implicated in the development of drug resistance in tumor cells." (PMID 37444616, 2023). "The overexpression of YY1 is linked to tumor cell resistance to cell-mediated immunotherapies." (PMID 37686541, 2023). "Several studies have found that higher levels of YY1 are associated with tumor growth, while other studies found that lower levels of YY1 may help to combat tumor invasion activity." (PMID 37686541, 2023). "Increased YY1 levels were linked to tumor metastasis and stage." (PMID 35791393, 2022). "Recent research has discovered that YY1 is linked to tumor immunity." (PMID 35791393, 2022). "YY1 can cause activation of oncogenes and suppression of tumor suppressors." (PMID 34276383, 2021). "Since Sox2 and Oct4 are essential for ESC biology; codetection of these proteins enables experimental isolation of CSCs, and targeting of these proteins inhibits tumor growth; thus, associations of YY1 with Oct4 and Sox2 suggest a possible role for YY1 in the CSC phenotype." (PMID 33728560, 2021). "Another study showed that KRAS mutation can activate the transcription factor YY1 through inflammatory NF-κB signaling, subsequently inhibiting the expression of the tumor suppressor gene miR-489, which affects the ability of PDAC cells to migrate and metastasize." (PMID 33985581, 2021). "Consequently, the modulatory ability of RKIP towards the NF-κB/YY1/Snail circuitry can be considered as one of the underlying mechanisms of RKIP-mediated inhibition of tumor chemo/immuno-resistance." (PMID 30149591, 2018). "Furthermore, a dysregulated NF-κB/Snail/YY1/RKIP loop can cause tumor cell resistance to cytotoxic drugs via inhibition of apoptosis." (PMID 28476134, 2017). "Over-expression of YY1 is associated with tumor progression and poor outcome in NHL, consistent with a hypothesis that attenuated YY1 binding at H2AFX rs643788 is associated with reduction in cancer risk." (PMID 24069324, 2013). "Considering that oncogenic activation of the EGFR pathway results in an immune-inert phenotype and recent literature has implicated a potential role of YY1 in mediating tumor immune escape, these conclusions may also be tentatively extrapolated to cancer immunotherapy." (PMID 39604408, 2024).
tumor (continued). "Our study is the first to suggest that YY1 expression is associated to the level of immune invasion of tumor-associated fibroblasts in some tumors, whereas the function of YY1 in tumor immunity and the tumor microenvironment is yet unknown, and the pathogenesis of tumor needs to be further explored." (PMID 35791393, 2022). "Mechanistically, tumor-derived lactate induced YY1 lactylation at lysine 183, facilitating YY1 nuclear entry and strengthening its combination with CARD9 promoter." (PMID 42212326, 2026). "In the present review, we highlight the function of YY1 in driving drug resistance in tumor cells, encompassing its regulation of survival pathways." (PMID 40867514, 2025). "In tumor cells, YY1 induces the transcription of the inhibitory immune checkpoint FGL1, which results in T cell apoptosis and the formation of an immunosuppressive microenvironment in lung adenocarcinoma." (PMID 41322030, 2025). "YY1 also acts as a pleiotropic factor interacting with various factors in the transcription initiation complex of tumor‐related genes, including SNAI1." (PMID 40145793, 2025). "In contrast, tumors assigned to the high-YY1-expression group exhibited strong, diffuse nuclear staining across the majority of tumor cells, reflecting marked YY1 upregulation in cancer cell nuclei." (PMID 41009346, 2025). "Our results show that YY1 overexpression is closely related to key aspects of tumor biology, such as immune evasion, metabolic weaknesses, and pathway‐specific alterations." (PMID 40088083, 2025). "While YY1 can suppress metastasis, several studies have also shown its capability to promote tumor growth." (PMID 41327312, 2025). "On the other hand, RKIP in its phosphorylated form is inactive resulting in the overexpression of YY1, NF-κB, and Snail which ultimately contribute to tumor progression, metastasis, and resistance to chemotherapy and immunotherapy." (PMID 41327312, 2025). "YY1 facilitates promoting tumor cell survival and resistance to apoptosis by suppressing the expression of death receptors, Fas and DR5, on anti-tumor CD8 T cells." (PMID 41327312, 2025). "Quantitative analysis of YY1 expression confirmed significant upregulation in tumor vs. normal tissues." (PMID 41009346, 2025). "Our goal was to evaluate YY1’s prognostic role with greater precision by quantifying its expression exclusively in tumor regions, minimizing bias from surrounding stromal tissues." (PMID 41009346, 2025). "Restoration of CRHR2/UCN2 signaling leads to miR-7 overexpression and decreased YY1 expression, thereby resensitizing tumor cells to FAS/FASL-mediated cell apoptosis." (PMID 40867514, 2025). "Compelling evidence indicates that YY1 modulates tumor immunity by regulating immune checkpoint molecules, influencing T cell differentiation and function, and modulating myeloid-derived suppressor cell (MDSC) polarization." (PMID 40867514, 2025). "In luminal tumors, YY1 acts as a transcriptional coactivator of ERα, enhancing tumor growth, correlated with poor prognosis." (PMID 41009346, 2025). "Here, we confirmed YY1 overexpression in tumor vs. normal tissue, consistent with previous reports in BC." (PMID 41009346, 2025). "Extensive studies have demonstrated that YY1, as an oncogene, regulates many pathways in tumor cell growth, metabolic reprogramming, invasion, and chemotherapy resistance." (PMID 40867514, 2025). "Several factors were significantly associated with OS, including molecular subtype, positive hormone receptor status (ER+ and PR+), nuclear grade, tumor size, axillary lymph node dissection, recurrence, prognostic stage (II–IV), and YY1 expression." (PMID 41009346, 2025). "Meanwhile, YY1 functions as a transcription factor with context-dependent roles, capable of either promoting or suppressing tumor growth based on its binding interactions." (PMID 41327312, 2025). "The expression of the transcription factor YY1 was elevated in both the precancerous and tumor groups compared to normal tissues." (PMID 39354287, 2025).
tumor (continued). "Mechanistically, overexpression of RKIP not only downregulates YY1 transcription but derepresses YY1-suppressors of death receptors and enhances tumor cell responsiveness to TRAIL-mediated apoptosis." (PMID 41327312, 2025). "Tumor-associated M2 macrophages and their YY1 are highly expressed, and LLPS of the YY1 complex upregulates interleukin (IL)-6 levels in the tumor microenvironment by promoting IL-6 enhancer-promoter interactions, leading to PCa progression." (PMID 40642070, 2025). "It has been proven that YY1 can be acutely modulated in cancer cells and that it can regulate genes related to cell cycle, cell death and tumor metabolism opening the possibility to use it as a novel target for therapeutic interventions." (PMID 39904836, 2025). "IHC revealed that the YY1 knockdown combined with anti‐PD‐1 treatment group had significantly increased CD8+ T cell infiltration within the tumor, while the GALNT16 overexpression group had reduced CD8+ T cell infiltration." (PMID 41322030, 2025). "Knocking down YY1 and combining it with anti‐PD‐1 therapy results in significant tumor shrinkage and increased CD8+ T cell infiltration." (PMID 41322030, 2025). "Overall, YY1 plays a key part in modulating tumor cell survival and chemoresistance within the TME by orchestrating important biological processes, such as metabolic reprogramming, immune evasion, and other cancer-associated pathways." (PMID 40867514, 2025). "In the tumor microenvironment, particularly in prostate cancer, YY1 is enriched in M2-like macrophages and promotes IL-6 expression, contributing to tumor progression." (PMID 41459495, 2025). "Due to its critical role in biological procedures, dysregulation of YY1 is tightly bound to diseases, including cardiovascular diseases, nervous system diseases, metabolic disorders, and tumor diseases." (PMID 40867514, 2025). "We found a clear nuclear localization of YY1 in tumor cells by IHC with occasional cytoplasmic staining." (PMID 41009346, 2025). "The optimal cutoff for medium-intensity nuclear YY1 expression in tumor areas for overall survival (OS) was established by a receiver operating characteristic (ROC) curve (AUC = 0.718, 95% CI: 0.587–0.849, p = 0.008)." (PMID 41009346, 2025). "Targeting the S-nitrosylation of YY1 offers a molecular intervention strategy to modulate NO-mediated effects and reverse tumor immune evasion mechanisms." (PMID 41036604, 2025). "Targeting this axis, by inducing RKIP or inhibiting YY1, should result in the inhibition of tumor growth and metastases as well as restoring cancer cells’ response to chemotherapeutic and immunotherapeutic interventions." (PMID 41327312, 2025). "While YY1 promotes tumor growth by stabilizing HIF-1α levels in some types of tumors, aberrant expression of YY1 results in ccRCC by increasing the expression of HIF-2α and inhibiting VHL." (PMID 40688406, 2025). "Subsequently, immunohistochemical staining for YY1, GALNT16, and PD‐L1 was conducted on human HCC consecutive tissue sections, and higher PD‐L1 expression levels were observed in tumor cells within tissues with high expression of YY1 and GALNT16." (PMID 41322030, 2025). "RKIP predominantly suppresses inflammation and tumor immune evasion whereas YY1 often promotes immunosuppression." (PMID 41327312, 2025). "YY1 expression was found across all BC molecular subtypes in our cohort, but YY1-positive tumor cells were enriched in TNBC." (PMID 41009346, 2025). "Higher YY1 expression was correlated with lower stromal and immune cell content in the tumor microenvironment." (PMID 40088083, 2025). "YY1 exhibits dual roles as a tumor suppressor and an oncogene, with aberrant expression detected in the majority of tumors." (PMID 41235100, 2025). "Multiple studies have investigated the role of YY1 in cancer therapy as dysregulation of its transcription holds significant promise due to its role in tumor progression, therapy resistance, and microenvironment regulation." (PMID 41327312, 2025).